Y_RNA (Y RNA )
Gene: Miscellaneous RNA gene on chromosome 17 (46,215,070 to 46,215,171, reverse strand). Ensembl gene ENSG00000238723.
Homologues: Orthologues: chimpanzee Y_RNA (99% identical), macaque Y_RNA (95% identical), dog Y_RNA (88% identical). Paralogues in human: Y_RNA (91% identical), RNY3 (90% identical), Y_RNA (90% identical), Y_RNA (89% identical), Y_RNA (88% identical), RNY3P1 (87% identical), Y_RNA (87% identical), RNY3P16 (86% identical), RNY3P4 (86% identical), Y_RNA (86% identical), RNY3P9 (85% identical), Y_RNA (85% identical), and 96 more.